RHOC (ras homolog family member C)
Diseases named in the same sentence as RHOC in open-access papers (continued):
Sharing a sentence is not in itself a finding about the gene and the disease.
cancer (continued). "Two other family members, RhoC and RhoT1, present a number of published mutations in cancer samples and cell lines, with the S73 residue a hotspot in RhoC, while mutations in RhoT1 include a P30L mutation, which by homology may have similar effects to the Rac1 P29S mutation." (PMID 27104658, 2016). "Promising results have been reported with a vaccine targeting the Ras homolog gene family member C (RhoC), a small GTPase overexpressed in advanced solid cancers, metastases and cancer stem cells." (PMID 41153826, 2025). "The Ras homolog gene family member C (RhoC) is a small GTPase which has a limited expression in normal cells but high expression in advanced cancer cells and metastases." (PMID 40333248, 2025). "Understanding the role of RhoC-regulated migration processes is crucial to deal with cancer metastasis mechanisms." (PMID 37671046, 2023). "Previous studies have shown that RHOC can regulate the invasion and metastasis of cancer cells and promote the progression of breast cancer, pancreatic cancer, lung cancer, ovarian cancer, and cervical cancer." (PMID 36771081, 2023). "Accumulated evidence indicates that adverse RhoC signaling affects angiogenesis and EMT processes, and is linked with cancer metastasis in different malignant tumors." (PMID 35314614, 2022). "Previous studies from our lab have found that macrophage-conditioned media, specifically from M2a macrophages, promotes cancer cell invasion, and that functional RhoC is necessary to achieve the full extent of macrophage-promoted invasion." (PMID 34513691, 2021). "The role of miRNA in regulating RhoC expression is indicative of the potential use of this mechanism in developing new cancer treatment schemes." (PMID 34627249, 2021). "Cell migration regulated by RhoC—of which the most well-known function is its role in cancer metastasis—has been widely reported in breast, gastric, colon, bladder, prostate, lung, pancreatic, liver, and other cancers." (PMID 34627249, 2021). "Studying RhoC functionality can contribute to a better understanding of cancer metastasis, as well as aid in development of new anti-metastasis therapeutic targets." (PMID 34627249, 2021). "In lung cancer, RhoC participated in the course of epithelial-mesenchymal transition induced by TGF-β1 in cancer cells." (PMID 34093823, 2021). "Previous studies have shown that RhoC promotes cancer development by regulating the expression of MMP genes in EMT." (PMID 33519932, 2021). "RhoC reportedly affects cell movement by influencing the activities of actin and myosin, and cell adhesion, thereby affecting the process of cancer metastasis." (PMID 34627249, 2021). "We believe that understanding the detail of RhoC-regulated migration processes will help us better comprehend the mechanism of cancer metastasis." (PMID 34627249, 2021). "High-resolution imaging demonstrated that RhoC-overexpressing cancer cells invade tissues by extending small membrane protrusions and vesicles—a typical amoeboid migration pattern—in a zebrafish xenotransplantation model." (PMID 34627249, 2021). "IQGAP1 stimulates filopodia formation, and promotes cell motility and invasion in mammalian and cancer cells, particularly through the interaction with β-catenin, e-cadherin, and small GTPase, i.e., Cdc42, Rac1, and RhoC." (PMID 32824461, 2020). "Collectively, these studies and many more demonstrated how the abnormal RhoC expression in multiple cancer cell types contributes to the invasiveness and metastatic ability of cancer cells through VEGF signaling." (PMID 32377503, 2020). "Cancer cell metastasis is also regulated by RhoC expression, whereby knocking down RhoC has been reported to reduce cancer cell migration." (PMID 32089990, 2020). "Several members of the Rho family of GTPases have been in the context of cancer angiogenesis, migration, and invasion, most notably RhoA, RhoB, RhoC, RhoG, Rac1, and Cdc42." (PMID 32089990, 2020).
cancer (continued). "This is in accordance with previous reports which described antagonistic roles of the 2 isoforms RHOA and RHOC, albeit during cancer cell invasion." (PMID 30781697, 2019). "In cancer cells, RhoC has been identified as a miR‐138 target gene via luciferase reporter assays, and our studies showed that RhoC protein levels were indeed lower in DDCs following miR‐138 overexpression." (PMID 30828688, 2019). "Following this study, several other groups reported the role of RhoC in numerous other cancers, including those of the breasts, skin, ovaries, liver and head and neck, among several others." (PMID 31340863, 2019). "While RhoC is imperative for developmental processes, RhoC is also a crucial regulator of metastatic progression in various cancers likely due to its dysregulation." (PMID 31214501, 2019). "It is becoming apparent in the cancer field that there is a regulatory link between miR‐138 and RhoC." (PMID 30828688, 2019). "RhoC has been demonstrated to regulate migration, cell cycle progression and various transcriptional networks in cancer cells." (PMID 31488179, 2019). "RhoC (Ras homolog gene family member C) regulates cytoskeletal organization and affects the motility of cancer cells favoring invasion and metastasis as well as progression and VM formation." (PMID 31993365, 2019). "RhoC is classically a cytosolic protein which regulates cytoskeletal organization and cancer cell motility." (PMID 31488179, 2019). "We pursued RhoC further given its function in regulating cell proliferation and migration in cancer cells." (PMID 30828688, 2019). "These and several more studies elucidate the mechanisms of RhoC-mediated regulation of cancer phenotypes." (PMID 31340863, 2019). "Considering its extensive contribution to carcinomas and their progression, it is important to initiate studies to define RhoC as a potential therapeutic target." (PMID 31340863, 2019). "The role of RhoC in carcinoma progression has been extensively clarified by several research groups over the years." (PMID 31340863, 2019). "There are several pathways, which are regulated by RhoC, that contribute to carcinoma progression and maintenance." (PMID 31340863, 2019). "The amazing results of pre-clinical studies indicate that RhoA and RhoC have different clinical roles in regulating transcriptional factors, invasion and metastasis of cancer cells in multiple cancers and are overexpressed in various solid tumors." (PMID 29861465, 2018). "RhoA and RhoC are the key drivers for cancer aggressiveness e.g., increased cellular proliferation and metastasis by activating several pathways that catalyze cell survival and proliferation." (PMID 29861465, 2018). "It has been well-established in many studies that RhoA and RhoC are pro-tumorigenic in almost all cancer types." (PMID 29385717, 2018). "Although RhoC is extensively expressed in almost all cancers, its clinical role and efficient treatment modality should be investigated for using it in the clinical setting." (PMID 29861465, 2018). "Because of the several unique post-translational modifications that are distinct from RhoA and RhoC, RhoB is argued to be the most diverse protein of the Rho subgroup, a factor possibly contributing to its dualistic role in cancer." (PMID 29385717, 2018). "Despite the technique’s novelty, the roles of RhoA and RhoC are being searched for successful management of cancer for further advancement in the future." (PMID 29861465, 2018). "Studies indicates that miR372 inhibits the Ras homolog gene family member C (RhoC) and p62 in human cancer cells." (PMID 28467776, 2017). "Unbiased gene ontology mining uncovered several cancer-associated/oncogenic proteins with elevated expression in MDCKYBX1 exosomes, including signalling proteins (K-Ras, RhoC, Rac1, and H-Ras)." (PMID 26919098, 2016).
cancer (continued). "This led us to determine the expression of relevant genes, which are involved in the promoting role of RhoC in malignant tumors after transfection with miR-372 in EC cells." (PMID 26673619, 2016). "Previous work has shown indoleamine 2,3-dioxygenase (IDO) and Ras homolog gene family member C (RhoC) to be promising antigen targets for inclusion in vaccines against multiple cancer forms." (PMID 26442104, 2015). "It will be interesting to observe if RhoC or Cdc42 that we describe to be important for cancer cell: EC interaction give an advantage for their survival in the microenvironment surrounding the vessels." (PMID 25677806, 2015). "Our results suggest that RhoC predominantly affects lung metastasis by affecting the step of cancer cell interaction with ECs." (PMID 25677806, 2015). "Our results indicate RhoC plays a central role in cancer cell interaction with vascular ECs, which is a critical event for cancer progression." (PMID 25677806, 2015). "This is consistent with our previous observations that RhoA and RhoC induce distinct phenotypes in cancer cells." (PMID 25677806, 2015). "Altogether, our in vitro and in vivo data show that RhoC is important for cancer cell interaction with ECs, and imply that this step is critical for cancer cell retention in blood vessels and subsequent metastasis formation." (PMID 25677806, 2015). "The pixel intensity of PECAM‐1 staining surrounding cancer cells in blood vessels was higher around RhoC‐depleted cells compared to control cells at 10 min after cell injection." (PMID 25677806, 2015). "This implies that RhoC would affect cancer cell invasion through the basement membrane after the TEM step as well as cancer cell: EC interactions." (PMID 25677806, 2015). "In a zebrafish model, RhoC works in cooperation with VEGF to enable cancer cell intravasation: RhoC increases the ability of cells to form specialized invadopodia to protrude through vascular EC openings." (PMID 25677806, 2015). "Depletion of the kinases ROCK1 and ROCK2, two known RhoC downstream effectors, similarly decreases cancer interaction with ECs." (PMID 25677806, 2015). "The effects of RhoC/ROCK depletion on cancer cell:EC interaction are thus different from RhoA depletion." (PMID 25677806, 2015). "We identify here the RhoC/ROCK pathway as a strong candidate for therapeutic targeting to reduce cancer metastasis, and indeed ROCK inhibitors have previously been shown to reduce experimental metastasis." (PMID 25677806, 2015). "Further study confirming our proposed compensatory mechanism is warranted, as is a deeper understanding of the overlapping and differential functions of RhoA, RhoC and other related Rho GTPases in cancer biology." (PMID 26030593, 2015). "This indicates that RhoA and RhoC act in different ways to affect cancer cell: EC interaction even though they both contribute to the initial step of cancer cell adhesion to ECs." (PMID 25677806, 2015). "Here we report that RhoC regulates the interaction of cancer cells with vascular endothelial cells (ECs), a crucial step in the metastatic process." (PMID 25677806, 2015). "Our results show that RhoC regulates the extension of protrusions by cancer cells along ECs in vivo, which correlates with effects on early cancer cell retention in the lungs and long‐term experimental metastasis." (PMID 25677806, 2015). "Specifically, studies in all types of cancers where RhoC expression was analyzed revealed a very strong correlation between greatly increased expression and metastasis." (PMID 24533098, 2014). "In our study, we have analyzed the effect of RhoC inhibition on the functional characteristics of cancer cells that exhibit CSC-like features in HNSCC cell lines." (PMID 24533098, 2014). "Up-regulation of RhoA and RhoC are essential for cell migration and cancer metastasis in various cancers." (PMID 23483935, 2013). "Although RhoA and RhoC share 92% identity, they have markedly different roles in motility and cancer." (PMID 24224016, 2013).
cancer (continued). "Previous studies have provided evidence suggesting the critical role of RhoC in promoting progression of different cancers." (PMID 23382905, 2013). "Some previous studies have revealed that RhoA and RhoC expression are frequently increased in human cancers, while RhoB is often down-regulated." (PMID 22860091, 2012). "IQGAP1 also participate the regulation of cancer cell proliferation as a downstream effector of RhoC." (PMID 23145020, 2012). "High FGF2 and RHOC levels exhibited a trend towards a correlation with worse patient survival (both overall and cancer-specific)." (PMID 22895562, 2012). "The results from Pile laboratory indicated that RhoA and RhoC siRNA represent powerful tools for inhibiting cancer cell proliferation, invasiveness, and angiogenesis both in vitro and in vivo." (PMID 23145020, 2012). "The acquisition of motility by otherwise stationary cells is an indicator of cancer progression and a process regulated across many cell lineages and cancers by RhoC." (PMID 22911725, 2012). "Most of what we know about the role of Rho GTPases in cancer cell invasion comes from the studies of the prototypic members RhoA, RhoB and RhoC, Rac1 and Cdc42." (PMID 22860091, 2012). "MiR-10b inhibits the synthesis of the HOXD10 protein and permits the expression of the pro-metastatic gene product RHOC, which in turn favors cancer cell migration and invasion." (PMID 21826246, 2011). "The reduction of RhoA and RhoC expression by RNA interference (RNAi) resulted growth inhibition of cancer cells." (PMID 20828398, 2010). "RhoC was identified in a screen for genes upregulated in melanoma metastases, and has subsequently been proposed as a marker for poor prognosis in cancers of different origins." (PMID 20822528, 2010). "There are surmounting evidences elucidating the contribution of two such pathways including Notch1 and RhoC to carcinoma progression." (PMID 19953094, 2010). "RhoC has been identified as an important player in metastasis and its expression correlates with metastatic spread of various types of carcinomas." (PMID 20615238, 2010). "Our data re-iterates the role of Notch1 in carcinoma progression and places RhoC as its downstream target." (PMID 19953094, 2010). "The downregulation of HOXD10 permits subsequently the expression of the prometastatic gene product RHOC, favoring, in turn, cancer cell migration and invasion." (PMID 19664288, 2009). "Many studies have been done in down-regulating the expression of RhoA and RhoC by RhoA or RhoC-specific siRNAs to inhibit the proliferation and invasiveness of cancer cells." (PMID 19374769, 2009). "RhoC GTPase is overexpressed in aggressive cancers that metastasize and is the predominant GTPase in PC." (PMID 15969750, 2005). "It has been postulated that a reduction in SC5D activity in cancer could promote the prenylation of Ras, Rac or RhoC, impacting cancer progression." (PMID 41596244, 2026). "RhoC plays a central role in cell migration and its role in cancer metastasis has been reported in several malignancies, including breast, gastric, colon, bladder, prostate, lung, pancreatic, and liver cancers, and, therefore, represents an attractive target for anticancer vaccination." (PMID 40333248, 2025). "Among these genes, the most overexpressed in platelet-educated cancer cells are those encoding proteins involved in cancer progression and metastasis, including SERPINE1 (358%), MMP2 (297%), MMP10 (214%), TIMP1 (187%), FN1 (166%), TMPRSS4 (146%) and RHOC (102%)." (PMID 40096084, 2025). "Since hAM preparations strongly reduced the migration of cancer urothelial cells, we further investigated their effect on the expression of key components required for efficient cell migration, such as cortactin, RhoA, RhoC, Cdc42 and Rac1." (PMID 37932474, 2023). "Similarly, RHOC was also proved to be the cancer therapeutic target due to its critical regulatory effects on cytoskeleton organization of cancer stem cells." (PMID 36290884, 2022).
cancer (continued). "RhoC is involved in cell migration and has been studied in many cancer types." (PMID 35420468, 2022). "Because either RhoC depletion or TJSR stimulation effectively blocks cancer cell growth and invasion, we suggest that the targeting of neddylation-dependent TJSR suppressors could be safer than NAE1 inhibition, as it would not stimulate prometastatic RhoC." (PMID 35354476, 2022). "Taken together, these results demonstrate that TDRG1 could be an alternative therapeutic target in EOC or other cancers through the inhibition of RHOC." (PMID 34771549, 2021). "To date, vital proteins related to cancer cell migration have been identified to include RhoA, RhoB, RhoC, Cdc42, Rac, and other members of the Rho GTPase family, the Ras superfamily, the WASP/WAVE family, the Scrib complex, and Par complex, PI3Ks and PTEN, PKCs, FAK, ERK, and Src, among others." (PMID 34627249, 2021). "One group showed that β-arrestin 1 regulates the spatial distribution of actin and actin regulators, leading to RhoC-mediated invadopodia formation in various cancers β-Arrestins have been emerging as critical regulators in cancers, making them potential targets." (PMID 34440828, 2021). "The consequent RhoC activity is poor, resulting in decreased motility of cancer cells." (PMID 34627249, 2021). "Herein, the role of RhoC in cancer cell migration is of particular interest." (PMID 34627249, 2021). "Therefore, we focused on a small GTPase called Ras homolog family member C (RhoC), which regulates cancer stemness, considering that a band of 20 kDa was detected by silver staining." (PMID 34285210, 2021). "RhoC belongs to Rho GTPases and plays a key role in various cancers." (PMID 31905344, 2020). "Additionally, RhoC is known to influence STAT3 in cancer, a relationship that can be blocked by drugs that affect lipid modification and therefore membrane localisation and activation of Rho-family proteins." (PMID 32915198, 2020). "The up-regulation of RhoC has been shown to increase invasion in cancer cells." (PMID 32824461, 2020). "RhoA and RhoC were frequently activated in many cancers and can stimulate malignant transformation." (PMID 31097692, 2019). "The role of RhoC in carcinoma progression has been well studied and reported." (PMID 31340863, 2019). "Intriguingly, while RhoC has been highly implicated in several aspects of carcinoma progression, there is no report of a mutation associated with this gene." (PMID 31340863, 2019). "The HOXD10 stainings are strong, strong, moderate and weak in para-carcinoma (× 100), well- (× 400), moderately- (× 400) and poorly-differentiated carcinoma (× 400), respectively, while the RHOC stainings are weak, weak, moderate and strong in the same carcinoma groups, respectively." (PMID 30683109, 2019). "Moreover, excessive expression of RhoA and RhoC are found to be more than 30% of all cancers which make them a vulnerable molecular target for cancer therapy." (PMID 29861465, 2018). "It was found that 90% of IBCs contain over-expressed RhoC GTPase gene which might be involved in growth and metastasis of cancer cells." (PMID 29861465, 2018). "Silencing of RhoC was found to inhibit the cancer-promoting effects of lncRNA ABHD11-AS1." (PMID 28818073, 2017). "Studies reveal that there are no known RHOC pathogenic mutations found in cancers, however, biologically relevant aberrant levels of RHOC expression are common, and there is a strong association between RHOC expression levels and poor prognosis." (PMID 28553926, 2017). "Unlike for Ras, no typical activating mutant of RhoC was detected in human tumors so far, but diverse missense mutations have been identified with low frequency in several cancer types (cbioportal.org)." (PMID 29152087, 2017). "This laboratory reported previously that STI1/HOP may have a role in cell migration by controlling cytoskeletal dynamics of cancer cells via mechanisms involving RhoC." (PMID 26847234, 2016).